ECRG4 (ECRG4 augurin precursor)
Diseases named in the same sentence as ECRG4 in open-access papers (continued):
Sharing a sentence is not in itself a finding about the gene and the disease.
colorectal carcinoma (8 papers, 2009 to 2025). A malignant epithelial neoplasm that arises from the colon or rectum and invades through the muscularis mucosa into the submucosa. "Further, ECRG4 promoter hypermethylation has been attributed to decreased expression in esophageal, prostatic, and colorectal cancers." (PMID 20598162, 2010). "Remarkably, aberrant methylation of ECRG4 was also found in primary human tumor tissues, including samples from colorectal carcinoma and from malignant gliomas." (PMID 20017917, 2009). "To evaluate the cellular effects of re-expression of ECRG4, we cloned the ECRG4 coding region and transiently transfected the gene into the colorectal carcinoma cell lines HCT116 and SW480." (PMID 20017917, 2009). "Overexpression of ECRG4 in colorectal carcinoma cells led to a significant decrease in cell growth." (PMID 20017917, 2009). "The ECRG4 coding region was cloned and transfected into colorectal carcinoma cells." (PMID 20017917, 2009).
esophageal squamous cell carcinoma (7 papers, 2011 to 2025). Esophageal squamous cell carcinoma (ESCC) is a type of esophageal carcinoma (EC) that can affect any part of the esophagus, but is usually located in the upper or middle third. "The ECRG4 gene was first described as a novel tumor suppressor gene associated with prognosis in esophageal squamous cell carcinoma (ESCC)." (PMID 23833667, 2013). "ECRG4 has been described as a novel tumor suppressor gene associated with prognosis in esophageal squamous cell carcinoma (ESCC)." (PMID 21288367, 2011). "Studies have shown that ECRG4 may induce the downregulation of COX-2 through the NF-КB pathway, thereby inhibiting tumor growth in esophageal squamous cell carcinoma (ESCC)." (PMID 36910669, 2023). "In China, C2orf40, also known as esophageal cancer-related gene-4 protein (ECRG4), was preliminarily identified and cloned by comparing the differential gene expression in normal esophageal epithelial cells and in esophageal squamous cell carcinoma (ESCC) cells." (PMID 35676661, 2022).
bladder cancer (6 papers, 2020 to 2025). "It has been observed in bladder cancer that ECRG4 promotes OGN expression by upregulating NFIC, preventing the activation of NF-KB downstream pathways, thus inhibiting cell proliferation and migration." (PMID 35197484, 2022). "Hence, ITIH5 and, in particular, ECRG4 might be promising candidates for further optimizing current bladder cancer biomarker panels and platforms." (PMID 32046186, 2020). "Both ECRG4 and OGN function as tumor suppressors in the bladder, with ECRG4 overexpression inhibiting NF-kB signaling and promoting NFIC/OGN signaling in bladder cancer cells." (PMID 40051609, 2025). "In the presented study, we focused on two putative tumor suppressor genes in bladder cancer that may also hold a prognostic impact, namely inter-α-trypsin inhibitor heavy chain 5 (ITIH5) and esophageal cancer-related gene 4 (ECRG4 or C2orf40)." (PMID 32046186, 2020). "We now provide evidence that ECRG4 and ITIH5 DNA methylation could be useful as urinary biomarkers for non-invasive bladder cancer detection." (PMID 32046186, 2020). "Therefore, we aimed to characterize the two putative tumor suppressor genes ECRG4 and ITIH5 as novel urinary DNA methylation biomarkers that are suitable for non-invasive detection of bladder cancer." (PMID 32046186, 2020). "Next, the biomarker quality of ECRG4 and ITIH5 promoter methylation was tested and then compared to a known putative bladder cancer methylation biomarker (NID2) by Methylation Sensitive Restriction Enzyme (MSRE) qPCR at the independent laboratories of Biotype GmbH (Dresden, Germany)." (PMID 32046186, 2020). "ECRG4 has also been described to be a candidate tumor suppressor gene that is inactivated by DNA methylation in cancers, like esophageal squamous cell carcinoma, breast cancer, renal cell cancer, and colorectal cancer, but not in bladder cancer so far." (PMID 32046186, 2020).
prostate carcinoma (6 papers, 2009 to 2025). A carcinoma that arises from epithelial cells of the prostate gland. "Previous studies reported on promoter hypermethylation and reduced expression of ECRG4 in advanced esophageal and prostate carcinomas and on a tumor suppressor function of ECRG4 in eosophageal cancer cell lines." (PMID 20017917, 2009).
gastric cancer (5 papers, 2019 to 2025). A primary or metastatic malignant neoplasm involving the stomach. "Overexpression of ECRG4 has been found to increase the sensitivity of gastric cancer cell line, SGC-7901 to 5-FU and NPC cell line, CNE1 to cisplatin, thereby improving the therapeutic effect of chemotherapy drugs." (PMID 36910669, 2023). "Further research revealed that ECRG4 was down-regulated to varying degrees in gastric cancer, breast cancer, hepatocellular cancer, nasopharyngeal cancer, laryngeal cancer, bladder cancer, glioma, colorectal cancer and prostate cancer." (PMID 36910669, 2023).
colon carcinoma (3 papers, 2009 to 2025). "ECRG4 was re-expressed in the colon cancer cell lines SW480, HCT116, HT-29 and the fibrosarcoma cell line HT1080 after treatment with the demethylating agent AZA." (PMID 20017917, 2009). "Thus, re-expression of the silenced ECRG4 gene as well as treatment of cells with ECRG4 protein significantly reduced colon cancer cell growth." (PMID 20017917, 2009). "As the three analyzed colon cancer cell lines showed ECRG4 hypermethylation, we asked whether ECRG4 methylation also can be found in primary colorectal tumors." (PMID 20017917, 2009).
Alzheimer disease (2 papers, 2021 to 2023). A progressive, neurodegenerative disease characterized by loss of function and death of nerve cells in several areas of the brain leading to loss of cognitive function such as memory and language. "Augurin, the protein encoded by C2orf40 (also called ECRG4), is involved in CNS development in animal models and shows association with neuropathologic features of Alzheimer’s disease and related dementias in humans." (PMID 34450027, 2021).
glioblastoma (2 papers, 2009 to 2024). The most malignant astrocytic tumor (WHO grade IV). "Seven out of 31 diffuse or anaplastic astrocytomas (23%), 12 out of 30 primary (40%) and 9 out of 10 secondary (90%) glioblastomas carried a methylated ECRG4 promoter." (PMID 20017917, 2009). "Statistical analysis revealed that ECRG4 methylation was significantly more frequent in secondary glioblastomas as compared to diffuse and anaplastic astrocytomas or primary glioblastomas (Fisher's exact test; p = 0.0003 and p = 0.0094, respectively)." (PMID 20017917, 2009).
hepatocellular carcinoma (2 papers, 2019 to 2020). A malignant tumor that arises from hepatocytes. "Although many studies have strongly suggested the role of ECRG4 as a potential tumor suppressor gene, some other reports have also demonstrated the oncogenic role of ECRG4 in patients with papillary thyroid carcinoma and hepatocellular carcinoma." (PMID 32922434, 2020).
invasive breast carcinoma (2 papers, 2011 to 2019). A carcinoma that infiltrates the breast parenchyma. "Using DNA microarray and array-based comparative genomic hybridization (aCGH), we examined ECRG4 mRNA expression and copy number alterations in 353 invasive breast cancer samples and normal breast (NB) samples." (PMID 22110708, 2011). "We searched for correlations between ECRG4 mRNA expression and histo-clinical features of tumors in a large data set of 1,387 invasive breast cancers, including our series and 5 public microarray data sets." (PMID 22110708, 2011).
rheumatic heart disease (2 papers, 2017 to 2023). An autoinflammatory condition following an infection with Group A Beta Hemolytic Streptococcus (GABHS), in which the heart is attacked by antibodies formed in reaction to a recent GABHS infection. "To explore the clinical relevance of Ecrg4 expression in atria and the conduction systems, we analyzed the expression of Ecrg4 by IHC in patients of rheumatic heart disease (RHD) with or without AF." (PMID 28578429, 2017).
atrial fibrillation (1 paper, 2023). A disorder characterized by an electrocardiographic finding of a supraventricular arrhythmia characterized by the replacement of consistent P waves by rapid oscillations or fibrillatory waves that vary in size, shape and timing and are accompanied by an irregular ventricular response. "As a result, this review summarizes the possible susceptibility gene, ECRG4 and its associated molecular mechanisms in cancer patients with atrial fibrillation and myocardial injury." (PMID 36910669, 2023). "Since down-regulation of ECRG4 is associated with atrial fibrillation, up-regulating ECRG4 expression may aid in treating atrial fibrillation." (PMID 36910669, 2023). "Downregulation of ECRG4 may increase the risk of atrial fibrillation by affecting ion channels, MMPs expression and inflammatory response." (PMID 36910669, 2023). "Studies have found that ECRG4 is implicated in the pathogenesis of atrial fibrillation." (PMID 36910669, 2023). "Moreover, since ECRG4 is a tumor suppressor gene, the downregulation of ECRG4 may also be a risk factor for atrial fibrillation in cancer patients." (PMID 36910669, 2023). "Other studies have shown that ECRG4 promotes cardiovascular homeostasis and prevents atrial fibrillation by regulating the response to ischemia/hypoxia." (PMID 36910669, 2023). "ECRG4 is known to regulate inflammation, induce neuronal senescence, participate in the formation of atrial fibrillation, and possibly act as a hypoxia sensor, contributing to myocardial injury." (PMID 36910669, 2023). "Additionally, certain drugs may affect ECRG4 expression and cause atrial fibrillation." (PMID 36910669, 2023). "Herein, we describe the ECRG4’s biological background, discuss its expression in the cardiovascular system, list the clinical and animal research related to the downregulation of ECRG4 in atrial fibrillation, and focus on its potential role in atrial fibrillation." (PMID 36910669, 2023). "Studies on ECRG4 in atrial fibrillation have also been conducted in animal models." (PMID 36910669, 2023). "The literature on atrial fibrillation induced by down-regulation of ECRG4 was summarized, and it was found that down-regulation of ECRG4 could induce atrial fibrillation through affecting ion channels, MMPs expression, and activating inflammatory response." (PMID 36910669, 2023). "The review begins by describing ECRG4’s biological background, discusses its expression in the cardiovascular system, lists the clinical and animal research related to the downregulation of ECRG4 in atrial fibrillation, and focuses on its potential role in atrial fibrillation." (PMID 36910669, 2023). "Additional investigations further concluded that ECRG4 could maintain cardiac homeostasis and regulate cardiac rhythm while it downregulation may contribute to atrial fibrillation (AF)." (PMID 36910669, 2023).
bladder tumors (1 paper, 2020). "Hence, a suitable impact was suggested, in particular for ECRG4, for discriminating BPH or urocystitis from bladder tumors, which is comparable with proposed biomarker candidates, like NID2 or TWIST1." (PMID 32046186, 2020).
chordoma (1 paper, 2014). Chordomas are rare malignant tumors arising from embryonic remnants of the notochord in axial skeleton. "We demonstrate the expression of new potential candidates for chordoma tumorigenesis, such as CD24, ECRG4, RARRES2, IGFBP2, RAP1, HAI2, RAB38, osteopontin, GalNAc-T3, VAMP8 and others." (PMID 24452533, 2014). "We could not analyze the prognostic impact of ECRG4 expression in chordoma." (PMID 24452533, 2014).
diabetes (1 paper, 2024). "The role of ECRG4 in regulating inflammation has only recently been identified and this is the first description of altered ECRG4 expression in diabetes." (PMID 39509414, 2024).
Ewing sarcoma (1 paper, 2012). A small round cell tumor that lacks morphologic, immunohistochemical, and electron microscopic evidence of neuroectodermal differentiation. "The expression of the selected target genes in Ewing’s sarcoma (CAV1, NR0B1, IGFBP3 and TGFBR2), together with the expression of HIST1H4L, KCNN2, ECRG4 and LDOC1, was then validated in an independent series of PCa with and without ETS gene fusions, as well as in a series of ESFT and ARMS." (PMID 23185447, 2012).
head and neck cancer (1 paper, 2013). A primary or metastatic malignant neoplasm affecting the head and neck. "ECRG4 has been shown to be a candidate tumor suppressor in several tumors, but its role in head and neck cancer remains poorly understood." (PMID 23833667, 2013). "In the present study, the effect of ECRG4 on head and neck cancer was investigated in vitro and in vivo. pFLAG-CMV-2-ECRG4 was stably transfected into squamous cell carcinoma of the head and neck (SCCHN) M2 cell lines to overexpress the ECRG4 gene." (PMID 23833667, 2013). "The head and neck epithelium is anatomically adjacent to the esophageal epithelium and although the majority of head and neck cancers are squamous carcinomas, no studies are available regarding the effects of ECRG4 on SCCHN." (PMID 23833667, 2013).
Hydrocephalus (1 paper, 2011). Hydrocephalus is an active distension of the ventricular system of the brain resulting from inadequate passage of CSF from its point of production within the cerebral ventricles to its point of absorption into the systemic circulation. "In light of the effects of Ecrg4 expression on cell proliferation (BrdU) and differentiation (nestin), it is more likely that this hydrocephalus phenotype is caused by increased ventricular cell proliferation resulting in obstruction of CSF flow and drainage during development." (PMID 21349154, 2011). "Inversely, gene knockdown of Ecrg4 in developing zebrafish embryos caused increased proliferation of GFAP-positive cells and induced a dose-dependent hydrocephalus-like phenotype that could be rescued by co-injection of antisense morpholinos with Ecrg4 mRNA." (PMID 21349154, 2011). "Finally, Ecrg4 gene knockdown using RNA interference targeting Ecrg4a in zebrafish embryos led to a hydrocephalus-like phenotype and increased GFAP-positive cell proliferation." (PMID 21349154, 2011). "The hydrocephalus-like phenotype observed in developing zebrafish after gene knockdown could therefore still support the hypothesis that one or more of the peptide products of Ecrg4 are involved in regulation of fluid balance." (PMID 21349154, 2011).
Hypercalciuria (1 paper, 2022). "Third, we assessed the potential role of Ecrg4 in kidney stone formation by challenging Ecrg4 KO and control mice with a diet inducing hypercalciuria and hyperoxaluria." (PMID 36227903, 2022). "We have previously identified Esophageal cancer-related gene 4 (Ecrg4) as being modulated by hypercalciuria." (PMID 36227903, 2022). "After having observed a response of Ecrg4’s expression to chronically induced hypercalciuria, we wondered if the increase in gene expression was segment-specific or was concerning all tubular segment in which Ecrg4 was found to be expressed." (PMID 36227903, 2022). "Considering a possible tubular adaptation to hypercalciuria in the case of chronic furosemide treatment, we checked for renal Ecrg4 mRNA expression after single furosemide treatment." (PMID 36227903, 2022). "Due to its higher expression in a hypercalciuric mouse model, we hypothesized that Ecrg4 mRNA is triggered by hypercalciuria and might modulate kidney stone formation." (PMID 36227903, 2022). "However, how cells sense hypercalciuria and increase Ecrg4 expression still remains to be identified." (PMID 36227903, 2022). "Thus, we propose that Ecrg4’s increased expression is triggered only by chronic and sustained hypercalciuria." (PMID 36227903, 2022). "We hypothesized that the increased expression of Ecrg4 mRNA is triggered by hypercalciuria and might modulate intratubular calcium-oxalate precipitation." (PMID 36227903, 2022). "We wondered whether Ecrg4 mRNA levels would be increased in other models of hypercalciuria." (PMID 36227903, 2022). "Finally, further studies will need to examine whether the limited renal insufficiency and hypercalciuria in the Ecrg4 KO mice is rather time dependent, or if there is a long-term adaptation mechanism, which might involve some other organs than the kidney." (PMID 36227903, 2022). "Ecrg4’s role in the kidney and especially in hypercalciuria is unknown." (PMID 36227903, 2022).
kidney stones (1 paper, 2022). "This study investigated the expression of Ecrg4 in the renal tissue, its regulation and its potential role in the development of kidney stones." (PMID 36227903, 2022). "For this, Ecrg4 KO mice were challenged with a kidney stone-inducing diet, rich in calcium and oxalate precursor." (PMID 36227903, 2022).
middle ear infection (1 paper, 2022). "Western blot analysis of middle ear tissue for ECRG4 protein showed expression only of the full-length, 14 kDa form prior to middle ear infection." (PMID 36092940, 2022).
Stroke (1 paper, 2024). Sudden impairment of blood flow to a part of the brain due to occlusion or rupture of an artery to the brain. "We found that a subgroup of oligodendrocytes (OL5) exhibited increased expressions of these DAO-associated genes such as Clu, Cd59a, Ecrg4, Ldha, Ldhb, etc. in both stroke and non-stroke hemispheres." (PMID 38509618, 2024).